IFNA14 (interferon alpha 14)
Description:
Produced by macrophages, IFN-alpha have antiviral activities. Interferon stimulates the production of two enzymes: a protein kinase and an oligoadenylate synthetase.
Synonyms: LEIF2H; IFN-alphaH
Tractability: Antibody: a drug acting on it is in phase 2 or 3 trials; its Gene Ontology location is reachable by antibodies, with high confidence; UniProt places it where antibodies can reach, with medium confidence; UniProt predicts a signal peptide or a membrane-spanning region.
Gene: Protein-coding gene on chromosome 9 (21,239,002 to 21,240,005, reverse strand). Ensembl gene ENSG00000228083.
Subcellular location: Secreted
Pathways (Reactome):
Immune System: Interferon alpha/beta signaling; Regulation of IFNA/IFNB signaling; TRAF6 mediated IRF7 activation
Disease: Evasion by RSV of host interferon responses; SARS-CoV-2 activates/modulates innate and adaptive immune responses
Hemostasis: Factors involved in megakaryocyte development and platelet production
Gene Ontology:
Molecular function: protein binding; cytokine activity; cytokine receptor binding; type I interferon receptor binding
Biological process: adaptive immune response; B cell activation involved in immune response; cellular response to virus; humoral immune response; natural killer cell activation involved in immune response; response to exogenous dsRNA; T cell activation involved in immune response; type I interferon-mediated signaling pathway; defense response
Cellular component: extracellular region
Genetic constraint (gnomAD): Loss-of-function variants: 1 observed, 0.29 expected, observed/expected ratio (o/e) 3.45. That is too few expected variants to judge how well the gene tolerates losing a copy. Missense variants: 337 observed, 221.55 expected, observed/expected ratio (o/e) 1.52, 90% interval 1.39 to 1.66. Synonymous variants: 113 observed, 78.85 expected, observed/expected ratio (o/e) 1.43, 90% interval 1.23 to 1.67.
Homologues: Orthologues: chimpanzee IFNA14 (98% identical), macaque IFNA14 (92% identical), pig IFN-ALPHA-13 (68% identical), pig IFN-ALPHA-9 (68% identical), pig IFN-ALPHA-15 (67% identical), pig IFN-ALPHA-8 (67% identical), pig IFNA1 (66% identical), pig IFN-ALPHA-4 (65% identical), pig IFN-ALPHA-17 (64% identical), rabbit IF1AD2 (64% identical), pig IFN-ALPHA-1 (63% identical), pig IFN-ALPHA-10 (63% identical), and 32 more. Paralogues in human: IFNA5 (85% identical), IFNA10 (84% identical), IFNA4 (84% identical), IFNA16 (84% identical), IFNA17 (83% identical), IFNA6 (83% identical), IFNA13 (83% identical), IFNA1 (82% identical), IFNA2 (82% identical), IFNA21 (82% identical), IFNA7 (81% identical), IFNA8 (81% identical), and 4 more.
Diseases named in the same sentence as IFNA14 in open-access papers:
IFNA14 is named in the same sentence as 15 diseases in open-access papers, as found by Europe PMC text mining. Sharing a sentence is not in itself a finding about the gene and the disease. The quoted sentences say what the papers report.
AIDS (1 paper, 2024). A syndrome resulting from the acquired deficiency of cellular immunity caused by the human immunodeficiency virus (HIV). "Additionally, patients with Acquired Immunodeficiency Syndrome (AIDS; stage C) showed significantly higher expression of IFNA1/13, IFNA8, IFNA14, IFNA16, IFNA17, and IFNA21 mRNA." (PMID 38543729, 2024).
cardiomyopathies (1 paper, 2025). "Moreover, JAK1 and IFNA16/IFNA14 can be used for constructing models to accurately identify the two cardiomyopathies." (PMID 39704101, 2025).
fungal infections (1 paper, 2017). "Genes exclusively regulated by atRA during fungal infections included CXCL6 for A. fumigatus challenge, and the fungal pattern recognition receptor Dectin-2 (CLEC6A) as well as the type-I interferons IFNB1 and IFNA14 during C. albicans infection." (PMID 28094291, 2017).
leukaemia (1 paper, 2022). "Finally, we evaluated the ability of IFNα14- or IFNβ-activated NK cells to control leukaemia in vivo." (PMID 36505400, 2022). "Importantly, adoptive transfer of IFNα14-activated NK cells significantly prolonged survival in a preclinical model of leukaemia compared to control NK cells expanded without IFN-I." (PMID 36505400, 2022). "Furthermore, adoptive transfer of IFNα14-activated, but not IFNβ-activated NK cells, resulted in significantly prolonged survival in our preclinical model of leukaemia." (PMID 36505400, 2022).
IFNA14 also shares sentences with these, for which no sentence is quoted: infection (7 papers); HIV-1 infection (6); viral infections (4); chronic hepatitis B (2); tumor (2); Autoimmunity (1); cancer (1); COVID-19 (1); lung disease (1); lupus nephritis (1); prostate carcinoma (1).